TLR4 (toll like receptor 4)
Diseases named in the same sentence as TLR4 in open-access papers (continued):
Sharing a sentence is not in itself a finding about the gene and the disease.
psoriasis (continued). "Analysis of the genome-wide transcription pattern of monocytes revealed IL6 as the top gene induced by S100 alarmin stimulation via interaction with TLR4, and targeted deletion of S100A9 ameliorated inflammation in a murine psoriasis model." (PMID 35543413, 2022). "Our data showed that psoriasis-like skin diseases activated TLR receptors based on skin lesions, which increased the expression of TLR2 and TLR4, and then activated MyD88 receptors and promoted the expression of MyD88 protein." (PMID 32090080, 2020). "Emerging evidence suggests that SARS-CoV-2 may trigger new-onset or exacerbate existing psoriasis, likely through viral protein-induced activation of toll-like receptors (TLR2 and TLR4)." (PMID 40558675, 2025). "Western blot results showed that IMQ promoted the expression of TLR4, MyD88, p-NF-κB p65 and p-IκBα, while PLE could reduce the protein levels of TLR4, MyD88, p-NF-κB p65 and p-IκB α in the skin of IMQ-induced psoriasis mice." (PMID 40333872, 2025). "Moreover, omega-3 polyunsaturated fatty acids can inhibit the binding of Toll-like receptor-4 (TLR4), thereby suppressing the expression of the NF-kB pathway and the secretion of pro-inflammatory cytokines, similar to the pathogenesis of psoriasis." (PMID 39170985, 2024). "Peripheral blood mononuclear cells were acquired from 10 severe psoriasis patients and administrated by different concentrations of recombinant‐HMGB1 (rHMGB1) to detect the Th17 cell percentage, mRNA and protein levels of TLR4, IL‐23, IL‐17A and retinoid‐related orphan receptor γt (RORγt)." (PMID 38414294, 2024). "Furthermore, the inflammatory indicators found to be upregulated in psoriasis MCs, such as ATF4, CXCL12, LTA, TACR1, TLR4, and CTSB, interestingly share IL-1β as a common modulator." (PMID 37681909, 2023). "In conclusion, elevated expression levels of TLR1, TLR2, TLR4, TLR7, and TLR9 may facilitate the occurrence of psoriasis." (PMID 34790055, 2021). "While this observation is in contrast with some reports, e.g., of a correlation between miR-146a and TLR4, IRAK1 in patients with coronary artery disease, others have observed reduced expression of IRAK1 by upregulation of miR-146a, e.g., in psoriasis and in senescent cells." (PMID 31294031, 2019). "Notably, both TLR4 inhibition and LCN2 neutralization alleviate psoriasis-like inflammation and NETs formation in both the IMQ model and K14-VEGF transgenic mice." (PMID 31024570, 2019). "It is plausible to speculate that both TLR4 and RAGE may be involved in the HMGB1-induced inflammation in psoriasis." (PMID 28769106, 2017). "This means the specific inflammatory reaction induced by nickel acting via Toll like receptor 4, activation of the inflammasome, and direct induction of keratinocyte apoptosis results in epidermal damage, but not in elimination of the psoriasis trigger." (PMID 25058585, 2014). "Furthermore, HMGB1 upregulates the expression of TLR2, TLR4, and RAGE in the skin lesion area of psoriasis and activates the inflammasome and NF-κB pathway in keratinocytes to promote IL-18 secretion, which would aggravate the condition of IMQ model psoriasis mice." (PMID 38255845, 2024). "Additionally, heat shock proteins (HSPs), such as HSP27, HSP60, HSP70, and HSP90, are overexpressed in KCs of psoriasis patients, and these HSPs can function as autoantigens to activate antigen-presenting cells (APC) through TLR4 to promote APC maturation and secretion of TNFα and IL12." (PMID 31815151, 2019). "Although it has been reported that the pathogenesis of psoriasis is related to TLR4/NF-κB or PI3K/AKT signaling pathway, the mechanism of action of PLE in the treatment of psoriasis has not yet been reported." (PMID 40333872, 2025).
glioma (63 papers, 2014 to 2025). A benign or malignant brain and spinal cord tumor that arises from glial cells (astrocytes, oligodendrocytes, ependymal cells). "The overexpression of TLR2 and TLR4 has been previously documented in glioma cell lines and tissue samples, with both receptors implicated in promoting glioma tumorigenesis." (PMID 40809181, 2025). "TLR4 activation has been predominantly linked to glioma progression and invasion via cytokines, chemokines, and type I IFN production." (PMID 41157253, 2025). "Moreover, PSAP stimulates glioma cell proliferation in vitro and regulates tumorigenesis through the toll-like receptor 4 (TLR4) associated to the nuclear factor kappa-light-chain-enhancer of activated B cells (NF-κB) signaling pathway." (PMID 36359323, 2022). "TREM1 shows significant enrichment in aggressive GBM subtypes and its inhibition functionally mediates anti-tumor effects by suppressing the glioma proneural-to-mesenchymal transition through modulation of the TLR4/PI3K/AKT/mTOR pathway." (PMID 41394801, 2025). "This discovery highlights the potential of targeting the TLR4/NF-κB signaling pathway as a therapeutic approach for glioma." (PMID 39708583, 2025). "TLR4 inhibition blocks PSAP-driven proliferation in gliomas, and inhibiting the PSAP/TGF-β1/Smad axis suppresses invasive growth in glioblastoma, and modulating PSAP expression enhances CD8+ T-cell responses against pancreatic cancer." (PMID 40801564, 2025). "The activation of the Toll-Like Receptor 4 (TLR4)/Nuclear Factor Kappa B (NF-κB) signaling pathway is strongly associated with the development of several types of cancer, including glioma." (PMID 39708583, 2025). "TLR2 and TLR4 were shown to be up-regulated in glioma samples and are negatively correlated with poor prognosis." (PMID 40809181, 2025). "The precise role of LCA in regulating the TLR4/NF-κB signaling pathway, its impact on glioma cell proliferation, and its effect on enhancing TMZ sensitivity have not been thoroughly elucidated." (PMID 39708583, 2025). "For instance, glioma grade IV has been shown to express lower levels of TLR4 compared to grade II-III gliomas." (PMID 40809181, 2025). "It has been shown that activation of TLRs, such as TLR4, in the glioma TME enhances MDSC recruitment and suppressive functions." (PMID 41157253, 2025). "PSAP overexpression in gliomas activates TLR4/NF-κB signaling, driving inflammatory factor release and glioma stem cell growth." (PMID 40801564, 2025). "The expressions of TLR2 and TLR4 have been previously examined in clinical glioma tissues and glioblastoma U87 cell lines." (PMID 40809181, 2025). "Some studies have shown downregulation of TLR4 in human U87MG glioma cell lines and human specimens resected from 8 patients with primary brain tumors." (PMID 40809181, 2025). "Our bioinformatics analysis further confirmed that TREM1 exerts anti-tumor effects in gliomas by targeting TLR4." (PMID 41394801, 2025). "To confirm the TLR4 impact on glioma cell migration, we preconditioned MSCs with TAK-242(1 μM), a specific TLR4 signalling pathway inhibitor." (PMID 38698968, 2024). "Another essential component that favors invasion is tenascin C. Gliomas are characterized by higher expression of tenascin C, which binds toll-like receptor 4 (TLR4) and induces M2 polarization of macrophages and microglia." (PMID 38473812, 2024). "The production of IL- 1β from glioma cells is responsible for the activation of TLR-4 and overexpression of HMGB1, which most likely gives rise to HLA-G, contributing to glioma immune evasion response." (PMID 38698968, 2024). "miR-23b-5p promotes chemosensitivity toward temozolomide by negatively regulating Toll-like receptor 4 (TLR4) in glioma." (PMID 36609391, 2023). "Inhibition of TLR4 signaling with shRNA induces chemotherapy-mediated apoptosis of glioma CD133+ cancer stem cells." (PMID 37723542, 2023).
glioma (continued). "Previous studies have reported that TLR4 is overexpressed in astrocytes, glioma cell lines, GBM tissues, and CD133+ cancer stem cells." (PMID 37723542, 2023). "In this study, we demonstrated that IOE inhibited LPS-induced TLR-4 activation and ROS overproduction in C6 glioma cells." (PMID 36670940, 2022). "The expression of TLR-4 and MyD88 was increased when LPS was treated with C6 glioma cells, but it was significantly (p < 0.05) diminished in C6 glioma cells treated with non-toxicological levels of IOE (0.1 and 0.2 mg/mL)." (PMID 36670940, 2022). "The subsequent correlation analyses also indicated MD2 was strongly correlated with CD14, LY86, TLR1 and TLR4 in gliomas." (PMID 35372062, 2022). "ROS overproduction induced by LPS treatment was remarkably reduced by NBP2–29328, an inhibitor of MyD88, providing direct evidence that TLR-4 activation is connected with ROS production in LPS-treated C6 glioma cells." (PMID 36670940, 2022). "TLR-4 signaling is a proinflammatory pathway also found in pediatric high-grade glioma and is promoted by miR-155 expression." (PMID 35326280, 2022). "TLR4 has also been reported to be associated with stem cell maintenance and chemoresistance induced by TMZ in gliomas." (PMID 35372062, 2022). "Microglia can regulate STAT 3 and NF-κB activity via mTOR, promote the immunosuppressive microglia phenotype to promote glioma immune escape, and upregulate their own IL-6 secretion via TLR4 as a mitogen for glioma stem cells." (PMID 36497459, 2022). "In glioma, activation of TLR4-mediated MyD88-dependent pathway was reported to correlate with upregulation of NF-κB signaling and increased expression of transcription factors (JUN and SRF), implying promoted cellular proliferation." (PMID 34715891, 2021). "A recent study has demonstrated that the silencing of TLR-4 gene in the U-87MG glioma cell line inhibited cell growth and induced apoptosis." (PMID 34439380, 2021). "In tissues and primary biopsies from glioma patients, the expression of TLR4 was significantly higher in grade IV GBM than in grade III anaplastic astrocytoma, correlating with poor prognosis." (PMID 34715891, 2021). "TLR4 stimulation also correlates with suppression of apoptotic molecule caspase-9 to stimulate glioma progression." (PMID 34715891, 2021). "GSCs also have cross talk with microglia and recruit GAM at glioma tumor site; GSCs-triggered GAMs release pro-inflammatory cytokine IL-6 via TLR4 signaling which is activated by GSCs-produced tenascin-C to promote glioma growth." (PMID 34715891, 2021). "TLR-4 activation in human glioma U251 cells stimulated the production of cytokines (IL-1β, IL-6, IL-8, and TNFα) and increased the expression of stem cell markers such as CD133 and CD34." (PMID 34439380, 2021). "Elevated TLR4 expression was observed in glioma tissues and cell lines compared with normal brain tissues." (PMID 34715891, 2021). "Prosaposin promotes the proliferation and tumorigenesis of glioma through TLR4-mediated NF-κB signaling pathway." (PMID 34552063, 2021). "PSAP, which together with CHCHD2 presented the lowest weights, has been pointed as a target for glioma treatment, by promoting glioma cell proliferation via the TLR4/NF- κB signaling pathway." (PMID 32070274, 2020). "LPS via TLR-4 stimulation changes immuno-phenotype in GSCs and the mature form of glioma cells and induces antitumoral response." (PMID 32354122, 2020). "Activation and TLR-4 downsignaling seem to play an interesting role in the promotion of glioma growth and invasion." (PMID 32354122, 2020). "For instance, overexpression of the lncRNA UBE2R2-AS1 promoted glioma cell apoptosis via targeting the miR-877-3p/TLR4 axis." (PMID 33643896, 2020). "Another interesting relation in glioma genesis is TLR-4/Programmed death receptor-1/Programmed death receptor-1 ligand (PD-1/PD-1L) axis interaction." (PMID 32354122, 2020).
glioma (continued). "Particularly, Toll-Like Receptor 4 (TLR-4) RNA and/or protein expression has been detected in different glioma cell lines, in primary biopsies from glioblastoma patients and adjacent to non-neoplastic tissue." (PMID 30680070, 2018). "Our in vivo experiments showed that depending on TLR4 signaling, LPS pretreatment of tumor cells dramatically prolonged the survival of glioma-bearing rats." (PMID 28641579, 2017). "We investigated the function of TLR4 signaling in cytotoxic T lymphocyte (CTL)-induced cytolysis to glioma CD133+ CSCs." (PMID 28881826, 2017). "Further investigations are needed to elucidate TLR4-induced signaling pathways in the pathogenesis and immune evasion of glioma CD133+ CSCs." (PMID 28881826, 2017). "Knockdown of TLR4 by shRNA in glioma CD133+ CSCs inhibited LPS-stimulated CSC proliferation and reversed the inhibitory effect of LPS-induced glioma CD133+ CSCs on the cytotoxicity of CTLs." (PMID 28881826, 2017). "To study the activity of TLR4 in human glioma CD133+ CSCs, we incubated CD133+ CSCs isolated from CSCs derived from SF295 and U251 glioma cell lines with LPS at different concentrations and time points." (PMID 28881826, 2017). "In this study, we found that TLR4 mRNA and protein was expressed in glioblastoma clinical samples and glioma cell lines." (PMID 28641579, 2017). "Depending on TLR4 signaling, LPS stimulation can result in an immunoreactive phenotype of glioma cells and GSCs." (PMID 28641579, 2017). "Flow cytometry and Western blot analysis demonstrated that TLR4 protein was expressed in six human CD133+ glioma CSCs." (PMID 28881826, 2017). "The bacterial component LPS dramatically alters the immuno-phenotype of glioma cells and GSCs via TLR4 signaling, which enhances glioma immunogenicity and elicits antitumoral immunity, thereby providing a new perspective for glioma immunotherapy." (PMID 28641579, 2017). "This study examined the ability of lipopolysaccharide (LPS) to affect glioma and glioma stem-like cells (GSCs) in vitro and to induce antitumor immunity in vivo and the role of TLR4 in these processes." (PMID 28641579, 2017). "We investigated the expression of TLR4 in human glioma CD133+ CSCs isolated from six CSCs derived from two glioma cell lines, SF295 and U251, and four fresh human surgical glioma tissues, patient (pT) 1 to pT4." (PMID 28881826, 2017). "Because overexpression of toll-like receptor 4 (TLR4) correlated with cancer development, we investigated LPS-induced TLR4 signaling in glioma CD133-positive (CD133+) CSCs." (PMID 28881826, 2017). "In microglia sorted from rat C6 gliomas, genes characteristic for M1 activation: Tlr2, Tlr4 and Il18, Cd80, Il12a, Il15 were significantly downregulated." (PMID 29242629, 2017). "One important line of investigation for the future is to perform in vivo studies of human glioma cell lines in humanized mouse models in order to fully understand the nature of the anti-tumor and pro-tumor effects of TLR4 and TLR9 agonists." (PMID 25411122, 2014). "One potential way to bypass these particular challenges due to the expression of TLR4 on glioma cells is through the activation of the Fas pathway." (PMID 25411122, 2014). "Considering the heterogeneous nature of gliomas, ranging from low to high grade with different therapeutic responses, investigating the differences in the levels of TLR2 and TLR4 and associated inflammatory markers in these distinct groups is of great clinical significance." (PMID 40809181, 2025). "TLR4 expression in gliomas has been variably reported in the literature." (PMID 40809181, 2025). "LCA could inhibit the proliferation and metastasis of glioma cells and reverse drug resistance, possibly by inhibiting the TLR4/NF-κB signaling pathway." (PMID 39708583, 2025). "Furthermore, our rescue experiments employing the TLR4 agonist RS09TFA established that TLR4 activation can partially counteract the PMT suppression resulting from TREM1 inhibition in glioma." (PMID 41394801, 2025).
glioma (continued). "Furthermore, TLR-4 was found to be overexpressed in gliomas and correlated with increased cellular proliferation, while glioma U251 cell lines treated with the TLR-4 lipopolysaccharide (LPS) ligand had enhanced tumor growth and decreased survival." (PMID 39202716, 2024). "In addition, we evaluated the correlation between the expression of the top 3 hub genes, STAT3, FOS and TLR4, in the grade 4 glioma tissue and model 1 miRNAs, miR-362-3p and miR-6721-5p, in serum." (PMID 38455766, 2024). "Curcumin may exert its anti-tumor effects in glioma cells by inhibiting the TLR-4/MYD88 pathway and inducing tumor cell apoptosis." (PMID 36429083, 2022). "Previous studies have assessed the impact of proton pump inhibitors on the nuclear factor kappa B (NFkB) and toll-like receptor 4 (TLR4) signaling pathway in gastric epithelial and cancer cells, kidney epithelial and tubular cells, monocytes, umbilical vein ECs, and glioma cells." (PMID 35563731, 2022). "We also found that IOE could effectively attenuate the LPS-induced activation of TLR-4/MyD88 dependent signaling pathways, resulting in reduced expression of inflammatory mediators in mouse brains and C6 glioma cells." (PMID 36670940, 2022). "Toll-like receptor 4 promotes glioma proliferation by activating the NF-kappa B signaling pathway." (PMID 33750478, 2021). "This suggests that modulating TLR4-dependent Wnt signaling and apoptosis could be a potential therapeutic strategy in the treatment of gliomas." (PMID 34715891, 2021). "In addition, partial colocalization of TLR4 with clathrin at the plasma membrane was observed in the HEK293 transfectants and in U373 glioma cells transfected with TLR4 and CD14." (PMID 33057840, 2021). "Additionally, the TLR4 pathway has been described to trigger apoptosis in glioma in a TRIF-dependent pathway." (PMID 33446690, 2021). "Furthermore, there is strong evidence that the expression of TLR4 interferes with Wnt signaling and apoptosis in glioma progression." (PMID 34715891, 2021). "These authors also found that HA synthesis by glioma cells occurred during the proliferative phase, which is in line with our model of differentiating GSCs where upregulation of TLR4 and secretion of HA by intermediate precursor cells activate the NFκB transcriptional pathway." (PMID 29679017, 2018). "And LPS was used to investigate the function of the TLR4 signaling pathway in glioma CD133+ CSCs." (PMID 28881826, 2017). "LPS-activated TLR4 signaling promotes the proliferation of glioma cell lines." (PMID 28881826, 2017). "Our study demonstrated the importance of TLR4-induced effects on glioma CD133+ CSCs." (PMID 28881826, 2017). "However, another study demonstrates that TLR4 is expressed on human astrocytes and glioma cell lines GL261, U373MG, U118, and U87." (PMID 28881826, 2017). "We demonstrated that surface and total TLR4 protein is expressed in glioma CD133+ CSCs." (PMID 28881826, 2017). "IHC analysis demonstrated that TLR4 is expressed in the tissue of glioma patients." (PMID 28881826, 2017). "In addition, LPS alters the immuno-phenotype of glioma cells from immunosuppressive to immunoreactive in a time-dependent manner via the TLR4 pathway." (PMID 28641579, 2017). "Although opinions differ, it is accepted that TLR4 is expressed in glioma." (PMID 28881826, 2017). "TLR4 expression was analyzed in two glioma patients by immunohistochemistry (IHC)." (PMID 28881826, 2017). "However, TLR4 is highly expressed and functional in astrocytes and glioma cells raising questions about the significance of this phenomenon." (PMID 28641579, 2017). "Glia, neurons, and neural progenitor cells all express TLR2 and TLR4, and may contribute to the striking responsiveness of several glioma models to metronomic CPA-induced anti-tumor immunity seen in our studies." (PMID 25952672, 2015).